KRAS (KRas proto-oncogene, GTPase)
Diseases named in the same sentence as KRAS in open-access papers (continued):
Sharing a sentence is not in itself a finding about the gene and the disease.
lung cancer (continued). "An in vivo study on mouse KRAS (kirsten rat sarcoma viral oncogene homolog) has driven a lung cancer-demonstrated negative impact of long-term supplementation of n-acetylcysteine and vitamin E on metastasis formation." (PMID 32466263, 2020). "Unlike cancers driven by KRAS mutations, many EGFR inhibitors have been used in the treatment for lung cancers, including Erlotinib (Tarceva), Afatinib (Gilotrif), Gefitinib (Iressa), Osimertinib (Tagrisso), Dacomitinib (Vizimpro), and Necitumumab (Portrazza)." (PMID 32308773, 2020). "Similarly, NetICS identified AKT1, EGFR, KRAS, NRAS, and PIK3CA among the top 5% in lung cancer data sets." (PMID 32076369, 2020). "CDK4/cyclin D kinase constitutes an attractive pharmacological target for development of anticancer therapeutics, in particular in KRAS-mutant lung cancer patients, who have a poor prognosis and no targeted therapy available yet." (PMID 32104498, 2020). "Following this encouraging result, a further phase III clinical trial in KRAS-mutant lung cancer was conducted, which, however, failed to reproduce the significant benefit in patients treated with the combination compared with docetaxel alone." (PMID 31612108, 2019). "Single nucleotide mutations, including polymorphisms of epidermal growth factor receptor (EGFR), KRAS proto-oncogene, GTPase (KRAS), and rearrangements of the ALK receptor tyrosine kinase (ALK) gene, are also involved in the occurrence of low-grade metastatic adenocarcinoma-type lung cancer." (PMID 31245210, 2019). "Next, we tested four lung cancer tissue specimens harboring ALK fusion, EGFR mutation, KRAS mutation, or none." (PMID 30943926, 2019). "Portraying the spectrum of tumor recurrence mutations in the same patient without the oncogenic lung cancer driver mutations such as EGFR, KRAS, and EML4‐ALK is an integrative step of understanding lung cancer tumor progression." (PMID 30941903, 2019). "The western blot assay showed that BP-1-102 alone increased the protein levels of p-MEK and p-ERK in KRAS mutant lung cancer cells compared with cells without treatment, whereas in wild-type cells, BP-1-102 alone had little effect on their protein levels." (PMID 31484165, 2019). "This drug combination did not prove to be effective in lung cancers irrespective of KRAS mutant status." (PMID 30636931, 2019). "Results showed that the combination of IPA-3 plus auranofin abrogated the expression of total/phosphorylation of PAK1, PKCι, ERK 1/2, mTOR, AKT, and YAP1 in the 3 lung cancer cell lines studied HCC827 (EGFR-mutant LUAD), H23 (KRAS-mutant LUAD) and H520 (PAK1 overexpression)." (PMID 31660987, 2019). "The combination showed potent antitumor effects in H358 xenografts and a PDX model of KRAS-mutant lung cancer without apparent toxicities." (PMID 31431614, 2019). "AZD-4785, a high-affinity constrained ethyl-containing therapeutic ASO targeting KRAS mRNA, potently depleted KRAS mRNA in KRAS-mutant colon, pancreatic, and lung cancer cell lines, with no feedback activation of MAPK signaling." (PMID 31470511, 2019). "In mutant KRAS lung cancer xenografts and genetically engineered mutant KRAS-driven lung cancer models, KRA-533 suppressed malignant growth without significant toxicity to normal tissues." (PMID 30971271, 2019). "High AIF expression was negatively correlated with poor prognosis, irrespective of the KRAS mutational status, suggesting that AIF overexpression is a common event in lung cancers associated with poor prognosis." (PMID 31133695, 2019). "Although KRAS mutants have higher levels of activities than WT KRAS before KRA-533 treatment, KRA-533 induces a dose-dependent increase in activity of WT and mutant KRAS in cell-free GDP-GTP exchange assay and in lung cancer cells." (PMID 30971271, 2019).
lung cancer (continued). "We analyzed the Variant Caller Files generated by bioinformatics analyses and we retained all non-synonymous and splice variants found at 1% with at least 50 mutated reads both for KRAS/NRAS-positive and negative colon and lung cancer biopsies." (PMID 29765524, 2018). "KRAS-driven lung cancers are not targetable by currently approved therapies and represent a particularly aggressive form of NSCLC5." (PMID 30013058, 2018). "Our primary aim was to assess the lung cancer initiation potency of DEN in FVB/N strain and also determine the KRAS and EGFR status of the tumors which could later serve as a new model for NSCLC research." (PMID 29415661, 2018). "The exosomes secreted by lung cancer cells, which enrich various proteins, such as EGFR, KRAS, claudins and RAB-family proteins, and promote the development of lung cancer, are effective biomarkers for early diagnosis of lung cancer and the basis of targeted therapy." (PMID 30217217, 2018). "First, we compared fluid-phase uptake in KrasG12D MEFs and KRAS-mutant human pancreatic (MIA PaCa-2) and lung (A549) cancer cells with the corresponding KRAS wild-type cells (MEFs, BXPC-3 human pancreatic cancer cells, and H522 human lung cancer cells)." (PMID 30400219, 2018). "This is because Yap protein levels in AT1 cells isolated from KRAS-driven lung cancer were indistinguishable from control cells after KRAS induction for 6 weeks." (PMID 30353028, 2018). "PFS was not significantly different between the HER2-mutant and the KRAS-mutant lung cancers groups (5.1 vs 5.0 months, p = 0.971)." (PMID 29587667, 2018). "Additionally, KRAS mutant NCI-H1792 and NCI-H23 lung cancer cells also showed upregulated ciliogenesis and increased Hedgehog pathway activation in response to MEK inhibition." (PMID 29874589, 2018). "In contrast, STK38L knockdown failed to induce apoptosis in a KRAS mutant lung cancer cell line H358." (PMID 29108249, 2017). "In contrast to other driver oncogenes in lung cancer, such as EGFR and ALK, molecularly targeted drugs to KRAS have not yet been developed and therapeutic targeting of KRAS-mutated lung adenocarcinoma remains a huge challenge." (PMID 28380052, 2017). "As MUC1-C has been reported to confer KRAS independence in mutant KRAS lung cancer cells, it warrants investigation whether targeting ILK can mitigate the effect of MUC1-C overexpression on KRAS independence." (PMID 28692035, 2017). "Next, gene fusion analysis was performed on RNA from FFPE tissue from 169 lung cancers in the prospective 533-sample cohort, which did not harbor mutations in EGFR, KRAS or BRAF (referred to as triple-negative cases hereon)." (PMID 28415793, 2017). "In the first set, we performed three genome scale screens with the MEK inhibitor trametinib, in the NRAS-mutant lung cancer cell line H1299 (NRASQ61K), the BRAF-mutant lung cancer cell line HCC364 (BRAFV600E), and the KRAS-mutant lung cancer cell line CALU1 (KRASG12C)." (PMID 28145866, 2017). "Epidemiological studies of lung cancer showed that EGFR mutations occur more frequently in never smoker East Asia, while KRAS mutations occur more frequently in smokers and less common in never smoker East Asia." (PMID 28430611, 2017). "Likewise, in on-going clinical trials testing MEK and BRAF inhibitors in KRAS- and BRAF-mutant lung cancer, responses have been reported in some patients." (PMID 28145866, 2017). "Thus, targeting of KRAS by combing MEK, PI3K inhibitors and TSA overcomes drug resistance in lung cancer cells." (PMID 28152508, 2017).
lung cancer (continued). "We also examined the expression of G9A in lung cancer using the oncomine database, and found that G9A is upregulated in LUAD regardless of EGFR or KRAS mutation status." (PMID 28383547, 2017). "Tyrosine kinase inhibitors can be used to treat lung cancers associated with EGFR mutations, but tumors eventually become resistant, and effective treatments for KRAS-induced cancers are currently lacking." (PMID 29340023, 2017). "Furthermore, the discovery of driver oncogenes (e.g., EGFR, KRAS and ALK) has changed our understanding of and approach to treating lung carcinogenesis, which has highlighted the importance of the genotype in lung cancer research." (PMID 28035073, 2017). "No other examined mutations (EGFR, HER2, HER4, KRAS or BRAF) were found in the lung tumor specimen of the patient, suggesting that HER3-V855Ais the primary driver for the lung cancer pathogenesis." (PMID 26689995, 2016). "Therefore, our results suggests that EGFR-positive lung cancers exhibit more GGO components, less lymph node invasion, and a higher tendency to metastasize to other organs, compared to the KRAS- and ALK-positive subtypes." (PMID 27518729, 2016). "Importantly, this combination produced potent tumour regressions in a series of KRAS-mutant lung cancer models in vivo, such as LSL-KRASG12D mouse model and PDTX models, as well as orthotopic lung cancer models." (PMID 27193833, 2016). "Although it remains unclear whether KRAS status is directly related to the role of GSK-3α in lung cancer cells, we suggest that the function of GSK-3α in KRAS signaling might be regulated in a cell-type specific manner." (PMID 27049759, 2016). "This suggests that ATM knockdown can affect the response to MEK inhibition in both the presence and absence of KRAS or BRAF mutations, both of which are common in lung cancer." (PMID 27922010, 2016). "For metastatic colorectal and lung cancer patients, where treatment with anti-EGFR monoclonal antibodies is only effective in patients whose tumours are RAS wild type, sequencing 3 exons of KRAS and 3 exons of NRAS is required, and this will possibly also be the case for other tumour types shortly." (PMID 26919633, 2016). "Our model suggests that in a group of mutant KRAS lung cancers, EGFR is not the major upstream signaling activator, but that this role is also played by HER2 and HER3." (PMID 25992771, 2015). "For KRAS in colon cancer and EGFR in lung cancer previous studies have suggested that cfDNA may be a reasonable alternative to tumour-based genomic testing for determining mutation status." (PMID 26498688, 2015). "Given the high prevalence of lung cancer and the availability of targeted therapy, Chinese lung ADC patients without EGFR and KRAS mutations are recommended for HER2 and BRAF mutations detection, especially for those never smokers." (PMID 26102513, 2015). "TANK Binding Kinase 1 (TBK1) is a non-canonical IκB kinase that contributes to KRAS-driven lung cancer." (PMID 26656453, 2015). "We did not analyze cell culture supernatants from NCI-H358 lung cancer cell which are also KRAS mutant." (PMID 26581653, 2015). "Multiplex reactions were optimised on genomic DNA extracted from KRAS mutant cell lines and tested on DNA extracted from fixed tumour tissue from a cohort of lung cancer patients without prior knowledge of the specific KRAS genotype." (PMID 26413866, 2015).
lung cancer (continued). "The apparently negative association of KRAS and EGFR mutations is not a general phenomenon among known lung cancer proto-oncogenes." (PMID 26047463, 2015). "Lung cancers in never-smokers are more frequently associated with adenocarcinoma with EGFR mutations and less frequently with KRAS mutations." (PMID 25760072, 2015). "Nevertheless, the correlations between NSC-743380's anticancer activity and KRAS mutations in the NCI-60 cell lines and in the 50 tested lung cancer cell lines were not significant." (PMID 25514600, 2015). "A549 lung carcinoma cells in contrast do not have any known mutations in the PI3K/mTOR pathway, but a mutation in the Kirsten rat sarcoma viral oncogene homolog (KRAS) gene, which occurs in about 30 % of non small cell lung cancers." (PMID 26498922, 2015). "Cigarette and coal dust have been proven to be mutagenic factors of KRAS and BRAF in lung cancer." (PMID 25013473, 2014). "One of the most interesting aspects of the let-7 family is that the 3′ UTR of KRAS (as well as HRAS, NRAS and various members of RAS GTPase family) contains multiple let-7 binding sites and that the expression of let-7 in lung cancer is inversely correlated to KRAS expression." (PMID 25593996, 2014). "Kaplan-Meier survival curves demonstrated significantly reduced survival for N39-positive patients in each subset grouped by age, stage, EGFR/KRAS/ALK alteration status, and smoking history, with the exception of patients with stage II lung cancer, presumably reflecting the reduced sample size." (PMID 25146220, 2014). "Four known biomarkers (CHEK2 in both plasma and urine, CDKN1B, PCNA, and THBS1) were identified as false positives (red) in our breast cancer list, and seven (KRAS, GDNF in both breastmilk and plasma, MYCL1 in both blood and serum, CD40LG, CGA, CTAG1A, ERCC6, and HRAS) in our lung cancer list." (PMID 25379168, 2014). "Alternative pharmacological and genetic approaches to target the NF-κB pathway in KRAS-driven lung cancer also do not completely eliminate tumorigenesis." (PMID 24955217, 2014). "Others have shown that non-hotspot KRAS and NRAS mutations occurring in leukemias and rare ERBB2 mutations in lung cancer are functionally transforming." (PMID 23237847, 2013). "In the present study, the detection rate of EML4-ALK fusion gene increased from 1.0% (2/202 patients with unselected lung cancer) in the test set to 5.1% (8/158 patients with EGFR and KRAS mutation-negative adenocarcinoma) in the validation set." (PMID 23936355, 2013). "For lung cancers, the genomic panel comprises of ALK, EGFR, KRAS and BRAF." (PMID 23863689, 2013). "Further proving that mutations in the RAS-RAF-MAPK pathway often have one hit per tumor, these tumors had no other known mutations in genes often mutated in lung cancer, such as EGFR, KRAS, HER2, or PIK3CA, or BRAF." (PMID 22928112, 2012). "Furthermore, we observed a significant increase in expression of C1QB and C1QC in macrophages in KRASG12D-driven, but not non–KRAS-driven, lung cancer, recapitulating our findings in the L-iKRAS model." (PMID 39782689, 2025). "Moreover, considering there are some widely-used biomarkers for lung cancer such as EGFR, KRAS, and PD-L1, combination of these factors with ZHX factors may provide more accurate and precise methods for prediction of patient survival." (PMID 41480542, 2025). "However, unlike in lung cancer where up-regulated KRAS disrupts the circadian gene PER2 leading to increased activation of glycolytic pathways, this disruption is not observed in our patient’s tumor." (PMID 40523964, 2025). "However, a recent report in lung cancer suggests that CPS1 may be crucial for pyrimidine maintenance and DNA synthesis in KRAS mutant cells." (PMID 40000871, 2025).
lung cancer (continued). "IL-6 was essential for MAPK activation; even with oncogenic KRAS mutations, the absence of IL-6 halted cancer development in PDAC mouse models and was shown to prevent initiation while enhancing the progression of lung cancer driven by KRAS mutations." (PMID 40611261, 2025). "Lung cancer epitomises precision oncology, which centers on targeting molecular alterations such as Epidermal Growth Factor Receptor (EGFR), Kirsten Rat Sarcoma Viral oncogene homolog (KRAS) G12C and Anaplastic Lymphoma Kinase (ALK), found in 40%–50% of lung adenocarcinomas." (PMID 41333367, 2025). "Additionally, KRAS KD did not affect the expression of ABC transporters in KRAS-mutant lung cancer cells." (PMID 39960727, 2025). "Moreover, the presence of EMT in KRAS-mutant PRCC may limit its potential effectiveness, as it is a known intrinsic resistance mechanism in KRAS-mutant lung cancer." (PMID 41375035, 2025). "Independent of KRAS mutation status, substantial and statistically significant antineoplastic effects of CDK2 inhibition were observed in murine syngeneic and human PDX lung cancer models after CYC065 treatment, repressing primary and metastatic lung cancer growth in vivo." (PMID 40232858, 2025). "Interestingly, COX-IS was not elevated in KRAS-mutant tumors, demonstrating the advantage of utilizing a RAS transcriptional signature, rather than simply KRAS mutation status, to capture RAS signaling activity in human lung cancer." (PMID 38635884, 2024). "Here, we integrate studies in patient-derived and immunocompetent lung cancer models and clinical specimens obtained from patients on targeted therapy to uncover a focal adhesion kinase (FAK)-YAP signaling axis that promotes residual disease during oncogenic EGFR-, ALK-, and KRAS-targeted therapies." (PMID 38702301, 2024). "Therefore, the activation of Wnt/β-catenin, KRAS, and AHR pathways due to impaired kidney function may play a substantial role in the development of lung cancer." (PMID 38549355, 2024). "Notably, KRAS and BRAF can also be targeted to hamper lung cancer progression." (PMID 38841622, 2024). "Notably, KRAS, BRAF, ERBB2, PIK3CA, RET, ROS1, ALK, and NRTK1/2/3 have been proposed as prognostic markers, making substantial contributions to genotype-directed therapies for advanced lung cancer." (PMID 36619227, 2023). "Moreover, dimerization of CRAF, rather than its kinase activity, is essential for KRAS mutant-driven lung cancer." (PMID 38111008, 2023). "Knowing the characteristics of KRAS‐positive cancers, especially lung cancer that is KRAS‐positive with NGS of liquid biopsies (liquid KRAS‐positive) lung cancer, might help effectively detect KRAS‐positive lung cancers in clinical practice." (PMID 37751775, 2023). "In addition, KRAS promotes HIF1A-As2 expression via the induction of MYC, suggesting HIF1A-As2 and MYC form a double-regulatory loop to strengthen cell proliferation and tumor metastasis in lung cancer." (PMID 37041291, 2023). "Notably, treatment of lung cancer cells with the EGFR tyrosine kinase inhibitor, gefitinib, or the KRAS-G12C inhibitor, AMG 510, reduced CD47 expression, which is consistent with the newly discovered mechanisms of CD47 regulation by EGFR and KRAS." (PMID 37958404, 2023).